SRSF3 (serine and arginine rich splicing factor 3)
Diseases named in the same sentence as SRSF3 in open-access papers (continued):
Sharing a sentence is not in itself a finding about the gene and the disease.
triple-negative breast carcinoma (4 papers, 2022 to 2024). An invasive breast carcinoma which is negative for expression of estrogen receptor (ER), progesterone receptor (PR), and human epidermal growth factor receptor 2 (HER2). "SRSF3 stabilizes the mRNA of TAR DNA-binding protein-43 (TDP43) by inhibiting the NMD pathway in triple-negative breast cancer, thereby maintaining the stemness of breast cancer stem cells." (PMID 39034387, 2024). "Second, in triple-negative breast cancer, SRSF3 interacts with the splicing factor TDP43 to regulate various splicing events, including apoptosis, extracellular matrix remodeling, cell adhesion, and tumor cell metastasis." (PMID 39034387, 2024). "SRSF3 can also promote metastasis and anoikis resistance by enhancing the inclusion of CPEB2 exon 4 via binding to a “CAUCC” splicing enhancer, and producing full-length CPEB2B protein to activate the translation of TWIST1 and HIF1α in triple negative breast cancer." (PMID 37416784, 2023).
colorectal tumor (3 papers, 2018 to 2023). "The enhancement of miR‐17/20 processing following SRSF3 overexpression led to altered expression of their target mRNAs encoding key cell cycle regulators in mouse pluripotent cells, human cancer cell lines and primary colorectal tumours." (PMID 37306233, 2023). "SRSF3‐mediated enhancement in miR‐17 and miR‐20a processing promoted self‐renewal, distinguishing poorly differentiated stem cell‐like colorectal tumours." (PMID 37306233, 2023). "For instance, in addition to the induction of the MCC protein, β-catenin/TCF4-induced SRSF3 expression decreased Rac1b expression in colorectal tumor cells by increasing skipping of alternative exon 3b." (PMID 33072610, 2020). "Next, we examined protein expression levels of PTBP1, hnRNPA1, and SRSF3 in clinical colorectal tumor samples." (PMID 30279379, 2018). "The SRSF3 mRNA expression was significantly increased in colorectal tumor samples." (PMID 30279379, 2018).
Ewing sarcoma (3 papers, 2020 to 2022). A small round cell tumor that lacks morphologic, immunohistochemical, and electron microscopic evidence of neuroectodermal differentiation. "Depletion of hnRNPM, and even more of SRSF3, caused a significant reduction in the colony formation potential of Ewing Sarcoma cells." (PMID 32023846, 2020). "We also found that the expression of hnRNPM and SRSF3, which showed the strongest repression of exon 6A inclusion, is highly associated with the expression of DHX9 in Ewing sarcoma patients." (PMID 32023846, 2020). "SRSF3 depletion displayed a stronger effect than HNRNPM depletion on Ewing sarcoma sensitivity to chemotherapy treatment, in line with its stronger impact on DHX9 expression." (PMID 32023846, 2020). "Our study documents that SRSF3 and hnRNPM downregulation reduces Ewing sarcoma cell proliferation and increases Ewing sarcoma sensitivity to doxorubicin treatment." (PMID 32023846, 2020). "Our study now suggests an oncogenic role of SRSF3 also in Ewing sarcoma cells." (PMID 32023846, 2020). "Since high DHX9 expression correlates with poor prognosis, these results suggest that regulation of DHX9 expression by SRSF3 and hnRNPM could represent a prognostic factor in Ewing sarcoma pathogenesis." (PMID 32023846, 2020). "Importantly, downregulation of SRSF3 or hnRNPM sensitized Ewing sarcoma cells to doxorubicin, a genotoxic agent used in Ewing sarcoma chemotherapy." (PMID 32023846, 2020). "Thus, we suggest that modulation of SRSF3 and hnRNPM expression and their splicing signature could represent a novel therapeutic opportunity for combined and less aggressive therapy in Ewing sarcoma." (PMID 32023846, 2020). "Therefore, our study suggests that inhibition of hnRNPM or SRSF3 expression could be exploited as a therapeutic tool in Ewing sarcoma." (PMID 32023846, 2020). "Hence, our study suggests that inhibition of hnRNPM and SRSF3 expression or activity could be exploited as a therapeutic tool to enhance the efficacy of chemotherapy in Ewing sarcoma." (PMID 32023846, 2020). "Notably, DHX9 expression correlates with that of SRSF3 and hnRNPM in Ewing sarcoma patients." (PMID 32023846, 2020). "Downregulation of SRSF3 or hnRNPM can inhibit the expression of DHX9 and the proliferation of Ewing’s sarcoma cells, and enhance the sensitivity of Ewing’s sarcoma cells to chemotherapy." (PMID 36338707, 2022). "To evaluate the effect of these splicing factors on Ewing sarcoma cell proliferation, we performed colony assays with cells transfected with control siRNA or with si-HNRNPM and si-SRSF3 oligonucleotides." (PMID 32023846, 2020). "Collectively these results unveil a novel role for SRSF3 and hnRNPM in the regulation of DHX9 alternative splicing, which also impacts on Ewing sarcoma cell sensitivity to chemotherapeutic treatments." (PMID 32023846, 2020). "Remarkably, silencing of SRSF3 and HNRNPM, impacts on DHX9 expression as well as on Ewing sarcoma cell viability and proliferation, while it reduces survival of Ewing sarcoma cells to doxorubicin treatment." (PMID 32023846, 2020). "We identified hnRNPM and SRSF3 as key factors required to suppress exon 6A inclusion and maintain high DHX9 expression in Ewing sarcoma cells." (PMID 32023846, 2020). "In this study, by employing multiple approaches, we have now identified several splicing factors (SRSF1, SRSF3, and SRSF10, hnRNPK, hnRNPM, and FUS) as regulators of DHX9 splicing in Ewing sarcoma cells." (PMID 32023846, 2020). "Similar results were also obtained in SK-N-MC and LAP-35 Ewing sarcoma cells, even though HNRNPM and SRSF3 knockdown in LAP-35 weakly affected DHX9 alternative splicing." (PMID 32023846, 2020). "SRSF3 and hnRNPM regulate poison-exon inclusion in DHX9 and sensitize Ewing sarcoma cells to chemotherapy." (PMID 32023846, 2020).
Ewing sarcoma (continued). "Notably, the effect of SRSF3 knockdown on DHX9 protein expression and Ewing sarcoma cell viability was stronger than that elicited by hnRNPM, although displaying a milder effect on the inclusion of the alternative poison exon." (PMID 32023846, 2020). "To test whether SRSF3 and HNRNPM depletion had an effect on Ewing sarcoma sensitivity to chemotherapeutic agents, we treated TC-71 cells with doxorubicin." (PMID 32023846, 2020). "Furthermore, downregulation of SRSF3 or hnRNPM inhibited DHX9 expression and Ewing sarcoma cell proliferation, while sensitizing cells to chemotherapeutic treatment." (PMID 32023846, 2020). "Moreover, our work indicates that the silencing of hnRNPM and SRSF3, the strongest repressors of exon 6A, significantly reduces DHX9 expression and Ewing sarcoma cell survival, thus suggesting the functional relevance of their effects on DHX9 splicing regulation." (PMID 32023846, 2020). "Noteworthy, although we focused on the DHX9 poison-exon as a splicing target of SRSF3 and hnRNPM with direct relevance for Ewing sarcoma, our findings do not rule out possible effects of these RBPs on other splicing variants of the same or other genes in this disease." (PMID 32023846, 2020).
leukemia (3 papers, 2019 to 2024). A malignant (clonal) hematologic disorder, involving hematopoietic stem cells and characterized by the presence of primitive or atypical myeloid or lymphoid cells in the bone marrow and the blood. "Another argument for AS events was critical to improve the understanding of tumor resistance as the destruction of the activity of the splicing factor SRSF3 could lead to drug resistance in the immunotherapy of leukemia." (PMID 33062256, 2020). "However, inadequate SRSF3 in relapsed leukemia cells was at least partly responsible for the expression of the Δex2 isoform." (PMID 31658644, 2019). "Moreover, relapsed leukemia cells expressed lower amounts of SRSF3." (PMID 31658644, 2019).
lymph node metastasis (3 papers, 2016 to 2022). "In OSCC, SRSF3 overexpression is positively associated with high-grade tumors and lymph node metastasis, indicating that SRSF3 may promote the development of OSCC." (PMID 36505770, 2022). "Nonetheless, the correlation between SRSF3 expression and carcinogenesis and the progression of these cancers, such as histological features, lymph node metastasis, TNM stage, or overall survival, remains to be studied." (PMID 33072610, 2020). "We found a positive correlation between lymph node metastasis and expression of hnRNP A1 (p < 0.01) or SRSF7 (p < 0.01) and a negative correlation between lymph node metastasis and the expression of hnRNP H (p = 0.03) or SRSF3 (p < 0.01)." (PMID 26930004, 2016).
myocardial infarction (3 papers, 2022 to 2025). Gross necrosis of the myocardium, as a result of interruption of the blood supply to the area, as in coronary thrombosis. "Functionally, SRSF3 has been implicated in liver diseases, ischemic stroke, and acute myocardial infarction 29-31." (PMID 41208880, 2025).
poliovirus infection (3 papers, 2011 to 2016). An disease or disorder caused by infection with Enterovirus C. "During poliovirus infection, some virus-induced SGs are compositionally unique from stress-induced SGs, containing the splicing factor and viral IRES transacting factor (ITAF), SRSF3 (SRp20)." (PMID 27999393, 2016).
prostate carcinoma (3 papers, 2022 to 2025). A carcinoma that arises from epithelial cells of the prostate gland. "Hypoxia-induced reprogramming of RNA splicing machinery up-regulates the oncogenic splicing factor SRSF3, which promotes prostate cancer progression." (PMID 41468516, 2025).
acute lymphoblastic leukemia (2 papers, 2021 to 2022). Leukemia with an acute onset, characterized by the presence of lymphoblasts in the bone marrow and the peripheral blood. "Previous research attested that the alteration in SRSF3 expression in B-acute lymphoblastic leukemia (B-ALL) cells would influence the splicing process of CD19, and in return it could lead to the impaired recognition of anti-CD19 chimeric antigen receptor (CAR) in T-cells." (PMID 34571875, 2021).
Alzheimer disease (2 papers, 2023). A progressive, neurodegenerative disease characterized by loss of function and death of nerve cells in several areas of the brain leading to loss of cognitive function such as memory and language. "Among the top hub genes associated with the common factor, TOB1, RANBP9, HSPB3, and SRSF3 were also linked to neurodegenerative disorders, such as Alzheimer’s disease, Parkinson’s, and amyotrophic lateral sclerosis, through various pathways." (PMID 36959830, 2023). "SRSF3 has a certain relationship with many diseases, such as Alzheimer’s disease, glaucoma, bipolar disorder, the occurrence, and metastasis of various tumors, as well as chemotherapy resistance." (PMID 36764525, 2023).
breast tumor (2 papers, 2016 to 2025). "By the 18 months, Srsf3’s oncogenic role in the development of mouse breast tumor became more obvious." (PMID 40568073, 2025). "Analysis by immunohistochemistry of the expression of hnRNP A1, hnRNPH, RBM9/FOX2, SRSF1/ASF/SF2, SRSF2/SC35, SRSF3/SRp20, SRSF7/9G8 in breast tumors shows that the expression of hnRNP A1, but not the other tested RBPs, is associated with metastatic relapse." (PMID 26930004, 2016).
Cirrhosis (2 papers, 2020 to 2021). A chronic disorder of the liver in which liver tissue becomes scarred and is partially replaced by regenerative nodules and fibrotic tissue resulting in loss of liver function. "SRSF3 was found to be downregulated in human HCC samples, and recent studies showed SRSF3 was also reduced in NAFLD, NASH and cirrhosis liver samples in both human and mouse, and as a consequence, changes in the splicing of known SRSF3 target genes were observed (FN1, MYO1B, INSR, SLK)." (PMID 33716968, 2021).
embryonal carcinoma (2 papers, 2018 to 2023). A non-seminomatous malignant germ cell tumor characterized by the presence of large germ cells with abundant cytoplasm resembling epithelial cells, geographic necrosis, high mitotic activity, and pseudoglandular and pseudopapillary structures formation. "To directly address the relationship between SRSF3-regulated splicing activity and RNA binding, we analyzed published data of crosslinking and immunoprecipitation (CLIP) experiments in embryonic carcinoma cells." (PMID 29928511, 2018).
glaucoma (2 papers, 2021 to 2023). Increased pressure in the eyeball due to obstruction of the outflow of aqueous humor. "These RNA‐binding proteins (or their closely related family members) have demonstrated important roles in RNA‐regulation (including splicing, export, stability, polyadenylation, and translation); in addition, SRSF3 and HNRNPL showed associations with ocular disease, mainly glaucoma." (PMID 33973683, 2021).
oral cancer (2 papers, 2015 to 2026). "SRSF3, SRSF10, and SRSF11 show increased expression as the disease progresses, indicating their involvement in oral cancer progression." (PMID 41584036, 2026). "However, the expression and function of SRSF3 in oral carcinoma is unknown to date." (PMID 26416554, 2015).
ovarian tumors (2 papers, 2015 to 2020). "In human ovarian tumors, we found that SRSF3 was overexpressed in invasive ovarian cancer at all stages and its overexpression was critical for tumor cell growth and maintenance of transformation properties." (PMID 26282282, 2015). "Therefore, it is no wonder that almost all invasive ovarian tumors that we examined overexpressed SRSF3 and knockdown of SRSF3 induced growth inhibition and cell death." (PMID 26282282, 2015).
atherosclerosis (1 paper, 2024). A disease characterized by the build-up of fatty material and calcium deposition in the arterial wall resulting in partial or complete occlusion of the arterial lumen. "To investigate the potential role of SRSF3 in inflammatory macrophages, we examined its expression in ApoE−/− mice, a widely used model for atherosclerosis." (PMID 38921043, 2024). "However, additional investigations are warranted to understand the direct impact of SRSF3 on atherosclerosis and other inflammatory diseases." (PMID 38921043, 2024).
B-cell neoplasm (1 paper, 2024). A group of heterogeneous lymphoid tumors generally expressing one or more B-cell antigens or representing malignant transformations of B-lymphocytes. "Thus, enhancing the expression of SRSF3 may enhance the survival rate of individuals experiencing recurrent B-cell neoplasms." (PMID 39034387, 2024).
congestive heart failure (1 paper, 2017). Failure of the heart to pump a sufficient amount of blood to meet the needs of the body tissues, resulting in tissue congestion and edema. "Further, digoxin, a drug used to treat congestive heart failure, modulates the activity of CLKs and increases the ability of SRSF3 (aka SRp20) to alter HIV-1 pre-mRNA splicing." (PMID 27928057, 2017).
COVID-19 (1 paper, 2024). A disease caused by infection with severe acute respiratory syndrome coronavirus 2. "Therefore, prospective studies are needed to collect human lung tissue samples before SARS-CoV-2 infection and determine whether pre-infection levels of Dicer, XPO5, SRSF3, and hnRNPA3 are associated with COVID-19 severity." (PMID 39138195, 2024). "Herein, we show that decreased RNAi component (Dicer and XPO5) and splicing factor (SRSF3 and hnRNPA3) expression correlate with increased COVID-19 severity." (PMID 39138195, 2024).
invasive breast ductal carcinoma (1 paper, 2025). "SRSF3, as a splicing factor, is responsible for 23% of alternative RNA splicing events identified in 682 invasive breast ductal carcinoma patients and higher expression of SRSF3 was linked with shorter survival time and poorer prognosis." (PMID 40568073, 2025).
lung adenocarcinoma (1 paper, 2022). A carcinoma that arises from the lung and is characterized by the presence of malignant glandular epithelial cells. "Additionally, high expression of SRSF3 and DHCR24 was detected in other types of cancers, such as uterine corpus endometrial carcinoma and lung adenocarcinoma, suggesting that further investigations are required on the antitumor effects and underlying mechanisms of SFI003 in these cancers." (PMID 35501301, 2022).
mesenchymal tumors (1 paper, 2022). "Recent studies also show SRSF3 upregulation in mesenchymal tumors." (PMID 36251702, 2022).
ovarian insufficiency (1 paper, 2026). "For example, SRSF1 directly regulates the alternative splicing of premature ovarian insufficiency (POI)‐related genes in oocytes, whereas SRSF3 maintains transcriptome integrity through alternative splicing regulation." (PMID 41524182, 2026).
papilloma (1 paper, 2022). A benign epithelial neoplasm that projects above the surrounding epithelial surface and consists of villous or arborescent outgrowths of fibrovascular stroma. "Raft tissues and terminally differentiated cells in the papilloma and cervical tissues express very little or no SRSF3, thus supporting viral L1 expression and production of infectious virions." (PMID 35563334, 2022).